EEPD1 (endonuclease/exonuclease/phosphatase family domain containing 1)
Diseases named in the same sentence as EEPD1 in open-access papers:
EEPD1 is named in the same sentence as 19 diseases in open-access papers, as found by Europe PMC text mining. Sharing a sentence is not in itself a finding about the gene and the disease. The quoted sentences say what the papers report.
colorectal cancer (2 papers, 2015 to 2026). A primary or metastatic malignant neoplasm that affects the colon or rectum. "Our work establishes EEPD1 as a promising therapeutic target to overcome immune checkpoint blockade resistance in colorectal cancer." (PMID 41911490, 2026). "We tested this by analyzing mRNA expression of EEPD1 in newly resected colorectal cancer versus adjacent normal tissue." (PMID 26684013, 2015). "EEPD1 is over-expressed in nearly all colorectal cancers and large cell lymphomas, cancers whose treatment is based on agents that create replication stress." (PMID 26684013, 2015). "In the present study we analyzed EEPD1 expression in 181 new colorectal cancers, and found that EEPD1 was expressed an average of 2.3-fold higher than adjacent normal tissue in 171 of 181 cases." (PMID 26684013, 2015).
esophageal squamous cell carcinoma (2 papers, 2022 to 2024). Esophageal squamous cell carcinoma (ESCC) is a type of esophageal carcinoma (EC) that can affect any part of the esophagus, but is usually located in the upper or middle third. "Besides, lncRNA NORAD was reported to upregulate esophageal squamous cell cancer radioresistance via miR-199-a1/EEPD1." (PMID 35600868, 2022). "In esophageal squamous cell carcinoma (ESCC), elevated expression of lncRNA-NORAD in radioresistant ESCC cells was found to confer RT resistance via EEPD1/ATR/Chk1 signalling and by inhibiting pri-miR-199a1 processing and the exosomal transfer of miR-199a-5p." (PMID 38802766, 2024).
abdominal aortic aneurysm (1 paper, 2025). Enlargement and ballooning of the vessel that supplies arterial blood to the abdomen, pelvis and legs. "Therefore, targeting endothelial EEPD1 knockout also has the potential for prevention and treatment of abdominal aortic aneurysms." (PMID 40268512, 2025).
atherosclerosis (1 paper, 2025). A disease characterized by the build-up of fatty material and calcium deposition in the arterial wall resulting in partial or complete occlusion of the arterial lumen. "To elucidate the protective mechanism of EEPD1 knockout on endothelial cells in the context of atherosclerosis, we conducted high‐throughput RNA sequencing (RNA‐seq) across four experimental groups: siCon, siCon+TNFα, siEEPD1, and siEEPD1+TNFα." (PMID 40268512, 2025). "The detrimental role of EEPD1 in atherosclerosis and its protective effect in radiation‐induced cardiomyopathy are not contradictory." (PMID 40268512, 2025). "In our research, we revealed that EEPD1 is elevated in atherosclerosis and enhances ERK phosphorylation while deteriorating endothelial function and apoptosis; these impacts are further intensified by KLF4 suppression." (PMID 40268512, 2025). "The enhanced expression in atherosclerotic endothelium suggests a significant role of endothelial EEPD1 in atherosclerosis progression." (PMID 40268512, 2025). "Collectively, this study revealed that EEPD1 deletion can lead to amelioration of atherosclerosis through the KLF4‐EEPD1‐ERK axis." (PMID 40268512, 2025). "To assess the involvement of EEPD1 in atherosclerosis, we analysed the expression of EEPD1 mRNA expression in human atherosclerotic samples sourced from the NCBI Gene Expression Omnibus (NCBI/GEO)." (PMID 40268512, 2025). "Although EEPD1 was knocked out in macrophages, the overall phenotype suggested that the beneficial effects of endothelial EEPD1 knockout on atherosclerosis outweighed the adverse effects in macrophages." (PMID 40268512, 2025). "Moreover, EEPD1 ameliorates atherosclerosis by promoting cholesterol efflux through the LXR‐EEPD1‐ABCA1/G1 pathway." (PMID 40268512, 2025). "Knocking out EEPD1 can reduce endothelial apoptosis, potentially promoting endothelial cell proliferation and enhancing endothelial barrier function, which is indeed beneficial for relieving atherosclerosis." (PMID 40268512, 2025). "Several challenges currently exist in targeting EEPD1 for the treatment of atherosclerosis." (PMID 40268512, 2025). "However, the role of EEPD1 in cardiovascular diseases needs to be explored further, especially in atherosclerosis." (PMID 40268512, 2025). "We also believe that targeting EEPD1 for the treatment of atherosclerosis necessitates a strong focus on the vascular endothelium, and that intervention at a relatively early stage of atherosclerosis may yield better outcomes." (PMID 40268512, 2025). "Subsequently, we probed the impact of EEPD1 on endothelial apoptosis in atherosclerosis." (PMID 40268512, 2025). "Consequently, when considering EEPD1 as a target for clinical translation and intervention in atherosclerosis, its vascular endothelial specificity is of paramount importance." (PMID 40268512, 2025). "In addition to atherosclerosis, targeting EEPD1 may also have an impact on other cardiovascular diseases." (PMID 40268512, 2025). "Functional analysis revealed that increase in EEPD1 promotes ERK phosphorylation and significantly increases endothelial apoptosis and inflammation in atherosclerosis, which was abrogated by inhibition of ERK phosphorylation." (PMID 40268512, 2025). "Hence, targeting EEPD1 could be a promising therapeutic strategy for patients with atherosclerosis." (PMID 40268512, 2025). "Despite these findings, sufficient in vivo evidence for EEPD1's role in atherogenesis is still lacking, and the mechanisms by which EEPD1 influences endothelial inflammation and apoptosis in atherosclerosis are not yet fully elucidated." (PMID 40268512, 2025). "Nevertheless, the specific regulatory interactions between EEPD1 and ERK in the context of atherosclerosis have not been clarified." (PMID 40268512, 2025).
breast carcinoma (1 paper, 2017). "Thus, the cell death seen in BRCA1-deficient breast cancer cells with RAD52 depletion requires the HR endonuclease EEPD1." (PMID 29145865, 2017). "However, when EEPD1 is also depleted in the RAD52-depleted BRCA1-deficient breast cancer cells, the synthetic lethality is completely abolished." (PMID 29145865, 2017). "To test this hypothesis, we applied cell survival assays, immunofluorescence staining, DNA fiber and western blot analyses to look at the correlation between cell survival and genome integrity in control, EEPD1, RAD52 and EEPD1/RAD52 co-depletion BRCA1-deficient breast cancer cells." (PMID 29145865, 2017). "When EEPD1 was co-depleted with RAD52 in BRCA1-/- breast cancer cells, levels of micronuclei and nuclear bridges were reduced to levels comparable to those seen in control cells." (PMID 29145865, 2017). "When we measured HU-stressed replication fork degradation in BRCA1 mutant breast cancer cells we found that depleting RAD52 or EEPD1 led to less stressed replication fork degradation, but co-depletion of both restored degradation to control levels." (PMID 29145865, 2017). "In this study we show that EEPD1 is required for death of BRCA1 mutant breast cancer cells that have been depleted of RAD52." (PMID 29145865, 2017). "This study demonstrates that the synthetic lethality seen when RAD52 is depleted in BRCA1 mutant breast cancer cells depends on the HR endonuclease EEPD1." (PMID 29145865, 2017). "When XRCC4 or LIG4 were depleted in the EEPD1/RAD52 co-depleted BRCA1-deficient breast cancer cells, no significant reduction in cell survival was observed." (PMID 29145865, 2017). "MDA-MB-436 BRCA1-/- breast cancer cells were depleted of EEPD1 and/or RAD52 using siRNA." (PMID 29145865, 2017). "In addition, an increase of ~ 30% in clonal cell survival was observed in the EEPD1/RAD52/XRCC4 triple-depleted breast cancer cells compared to the EEPD1/RAD52 co-depletion cells respectively." (PMID 29145865, 2017). "Specifically we show that depletion of EEPD1 rescues the synthetic lethality of RAD52-depleted, BRCA1 mutant breast cancer cells." (PMID 29145865, 2017). "Our data show that depletion of EEPD1 suppresses synthetic lethality, genome instability, mitotic catastrophe, and hypersensitivity to stress of replication of RAD52-depleted, BRCA1 mutant breast cancer cells." (PMID 29145865, 2017).
cardiac hypertrophy (1 paper, 2024). "Thus,EEPD1 protects against radiation-induced cardiac hypertrophy and apoptosis via destabilization ofFOXO3A, which may offer new insight into therapeutic strategies for RIHD." (PMID 39210825, 2024).
cardiomyopathy (1 paper, 2025). A disease of the heart muscle or myocardium proper. "EEPD1 exerts protective effect against radiation‐induced cardiomyopathy by modulating the ubiquitination level of FOXO3A through its interaction with FOXO3A, thereby regulating the protein stability of FOXO3A." (PMID 40268512, 2025). "Previous study has also revealed that EEPD1 in the myocardium exerts protective effect against radiation‐induced cardiomyopathy through the EEPD1‐FOXO3A axis." (PMID 40268512, 2025).
glioblastoma (1 paper, 2023). The most malignant astrocytic tumor (WHO grade IV). "Our results suggest that for those cancers that are more susceptible to oxidative damage, such as glioblastomas targeting EEPD1 might present a novel therapeutic target." (PMID 36683914, 2023).
glioma (1 paper, 2023). A benign or malignant brain and spinal cord tumor that arises from glial cells (astrocytes, oligodendrocytes, ependymal cells). "While all cells had a decrease in survival to oxidative/alkylative damage after EEPD1-depletion, U-87 glioma cells, which arose in a hypoxic environment and are particularly sensitive to H2O2 when EEPD1 is depleted." (PMID 36683914, 2023).
ovarian carcinoma (1 paper, 2021). A malignant neoplasm originating from the surface ovarian epithelium. "Our results show that ADIRF, SLC2A5, C3orf86, HSPA1B are among the most significant PCa biomarkers, while MTRNR2L1, EEPD1, TEPP and VN1R2 are jointly important biomarkers across prostate, breast and ovarian cancers." (PMID 34001952, 2021).
cancer (10 papers, 2015 to 2026). A tumor composed of atypical neoplastic, often pleomorphic cells that invade other tissues. "Replication stress is increased in cells undergoing rapid cell division during early embryonic development and in cancer (oncogenic stress), and EEPD1 deficiency causes severe embryonic developmental defects." (PMID 38069223, 2023). "The mechanism by which RAD52 depletion causes synthetic lethality in BRCA1 mutant cancer cells depends on the 5′ endonuclease EEPD1, which normally functions to cleave stressed replication forks to initiate HR repair." (PMID 29145865, 2017). "One would predict that malignancies would require intact EEPD1 to proliferate, and that loss of function mutations would be rare in human cancers." (PMID 26684013, 2015). "Furthermore, cancer bioinformatics support oxidative damage-dependent EEPD1 association as a significant modulator of overall patient survival." (PMID 41830330, 2026). "EEPD1 is a structure-specific nuclease that is overexpressed in various tumors, but its mutation in cancer is uncommon, which may help tumor cells manage oncogenic stress or confer resistance to therapeutic agents." (PMID 37563740, 2023). "This may explain why mutations in EEPD1 are rare in cancers and the observation that EEPD1 is expressed at higher levels in most tumor types than in normal cells." (PMID 36683914, 2023). "Defect in EEPD1 predisposes cells to cancer due to its role in damage repair." (PMID 37818043, 2023). "Given their roles in DNA repair, damage signaling, and genome stabilization, it’s possible that defects in Metnase or EEPD1 might predispose to cancer, similar to other DDR factors like BRCA1, BRCA2, and ATM." (PMID 35155245, 2022). "We then investigated whether aNHEJ was the escape pathway utilized by the EEPD1/RAD52 co-depleted BRCA1-deficient cancer cells for survival." (PMID 29145865, 2017). "Targeting EEPD1 could block proliferation of cancers that depend on EEPD1, or sensitize tumors to chemotherapeutics that cause replication stress." (PMID 26684013, 2015). "Here, we integrate hybrid structural methods, evolution, biochemistry, cancer genomics, plus molecular and cell biology to define EEPD1 structure, assembly, and function at stalled DNA replication forks." (PMID 41830330, 2026). "Since BRCA1 is important for initiating end resection in normal cells, BRCA1-mutant cancer cells use EEPD1 to cleave stressed replication forks and initiate end resection during RAD52-mediated HR repair of stressed replication forks." (PMID 36683914, 2023). "This confirmed that REEP3, REEP4, TEP1, and EEPD1 and their network proteins were involved in immunoregulatory functions and cancer development." (PMID 37818043, 2023). "Taken together, REEP3, REEP4, TEP1, and EEPD1 were related to many cellular functions including cell proliferation, differentiation, the pathogenesis of neurological disorders and cancer biology." (PMID 37818043, 2023). "As a replication stress nuclease, EEPD1 was found to be overexpressed in various malignancies (e.g., brain, breast, kidney, lung) likely owing to its function of helping cancer cells cope with oncogenic stress (e.g., radiation, genotoxins)." (PMID 37818043, 2023). "Here we focus on Metnase and EEPD1 DNA repair pathways, and discuss opportunities for targeting these pathways to enhance cancer therapy." (PMID 35155245, 2022). "This study indicates that the mechanism of synthetic lethality in RAD52-depleted BRCA1 mutant cancer cells depends on the endonuclease EEPD1." (PMID 29145865, 2017). "We also assessed EEPD1 expression in a panel of fifteen untreated cell lines by western blot analysis and found that EEPD1 is expressed in all cancer and non-cancer cell lines, and thus could have a role in DNA repair that crosses tissue specificities." (PMID 36683914, 2023). "EEPD1 thus serves as a biomarker for stressed cancer cells and a target of cancer therapeutics." (PMID 37818043, 2023).
cancer (continued). "Novel combination therapies targeting upstream PIKKs and/or downstream replication stress nucleases MUS81, EEPD1 or Metnase, may be effective anti-cancer treatments on their own, or when combined with genotoxic chemo- and radiotherapeutics." (PMID 35155245, 2022). "Inactivating mutations in EEPD1 are not seen in cancers, but EEPD1 is overexpressed in subsets of cancers of the brain, breast, colon, cervix, kidney, skin, lung, prostate, head and neck, and uterus." (PMID 36203968, 2022). "Although mutations in Metnase and EEPD1 are not common in cancer, both proteins are frequently overexpressed, which may help tumor cells manage oncogenic stress or confer resistance to therapeutics." (PMID 35155245, 2022). "However, no gain or loss of function mutations in Metnase or EEPD1 have yet been verified in cancers; if they exist, they are likely to be rare." (PMID 35155245, 2022). "Thus, EEPD1 could be used as a biomarker for treatments that target RAD52 in BRCA1/2 mutant cancers." (PMID 29145865, 2017). "Given that depleting EEPD1 prevents synthetic lethality of RAD52 repression in BRCA1 mutant cancer cells, potential mechanisms by which cancer cells could become resistant to clinically useful RAD52 inhibitors are by repressing EEPD1 expression or acquiring EEPD1 loss-of-function mutations." (PMID 29145865, 2017). "When comparing NACT-treated samples with untreated ones in cancer patients the expression of TMEM51, NOTCH1, EEPD1, MAFB, and HLA-DRB5 remained increased in monocytes of treated patients." (PMID 39315092, 2024). "Taking advantage of Gene Expression Profiling Interactive Analysis (GEPIA) and The Cancer Genome Atlas Program (TCGA), we compared mRNA expression of REEP3, REEP4, TEP1, and EEPD1 between GBM tumor and normal brain tissue." (PMID 37818043, 2023). "Depletion of EEPD1 also reduced fork restart albeit to a lesser degree than RAD52 depletion in the BRCA1-/- cancer cells." (PMID 29145865, 2017). "It further suggests that while RAD52 inhibitors may prove effective in treating cancers with BRCA1 defects, resistance may arise if tumor cells suppress EEPD1 expression or otherwise inactivate EEPD1." (PMID 38069223, 2023). "Thus, our prior analysis of EEPD1 in BRCA1-mutant cells and the present results suggest that EEPD1 plays an important role in permitting BRCA1-mutant cancers to survive despite increased oxidative DNA damage including replication fork damage." (PMID 36683914, 2023). "Without HR and the RAD52-dependent backup pathway, the BRCA1 mutant cancer cells depleted of EEPD1 skew to the alternative non-homologous end-joining DNA repair pathway for survival." (PMID 29145865, 2017). "Thus, EEPD1 (and RAD51) overexpression likely confers a selective advantage to cancer cells as they manage multiple types of stress, and it is also likely to confer resistance to replication stress-inducing cancer chemo- and radiotherapeutics." (PMID 38069223, 2023). "Interestingly, our data showed that, unlike BRCA1 mutant MDA-MB-436 and SUM149PT cancer cells, BRCA1-depleted MCF7 cancer cells were not sensitive to EEPD1 depletion." (PMID 29145865, 2017). "Thus, even though loss of EEPD1 results in genomic instability, EEPD1 should not be viewed as a tumor suppressor in the same sense as BRCA1 and BRCA2, two HR components that show loss of function mutations in cancer." (PMID 26684013, 2015).
tumor (9 papers, 2015 to 2025). "Thus, targeting RAD52 may enhance treatment of BRCA-deficient tumors, but co-inhibition of RAD52 and EEPD1 would likely be self-defeating, enhancing tumor cell survival and potentially enhancing tumor progression by allowing severely damaged cells to survive." (PMID 35155245, 2022). "This study suggests EEPD1 as a promising avenue for creating new therapeutic agents, possibly with anti‐tumour effects." (PMID 40268512, 2025). "The GEPIA and TCGA datasets were used to analyze the expression patterns of REEP3, REEP4, TEP1, and EEPD1 in tumor tissue and normal tissue." (PMID 37818043, 2023). "The result showed that the expression of REEP3, REEP4, TEP1, and EEPD1 was significantly higher in GBM tumor tissue." (PMID 37818043, 2023). "As shown in, the REEP3, REEP4, TEP1, and EEPD1 had significantly higher expression in GBM tumor tissues compared to normal tissues." (PMID 37818043, 2023). "To evaluate REEP3, REEP4, TEP1 and EEPD1 mRNA levels in multiple tumor and normal samples, we downloaded and compiled data from 11124 samples (Tumor =7260, Normal =3864) from the TCGA database." (PMID 37818043, 2023). "REEP3, REEP4, TEP1 and EEPD1 was differentially expressed in 14, 17, 14, 13 tumor types, respectively." (PMID 37818043, 2023). "IHC staining of xenograft tumours showed that tumours derived from NORAD knockdown cells exhibited less EEPD1 staining." (PMID 34587992, 2021). "Xenograft tumours from EEPD1 knockdown and control cells showed that EEPD1 knockdown significantly sensitized ESCC cells to radiation in vivo." (PMID 34587992, 2021). "Thus, EEPD1 overexpression probably provides a selective advantage to tumor cells, and it may be an important contributor to tumor resistance to therapies that induce replication stress." (PMID 36203968, 2022). "Consequently, EEPD1 targeting may be more appropriate for atherosclerotic patients who require polypharmacy, particularly those with concurrent tumours, as opposed to colchicine, which is susceptible to drug–drug interactions." (PMID 40268512, 2025).
EEPD1 also shares sentences with these, for which no sentence is quoted: obstructive sleep apnea syndrome (2 papers); angiosarcoma (1); cardiovascular diseases (1); colon cancer (1); hyperlipidemia (1); large cell lymphomas (1); neurological disorders (1).